APOB (apolipoprotein B)
Diseases named in the same sentence as APOB in open-access papers (continued):
Sharing a sentence is not in itself a finding about the gene and the disease.
coronary artery disease (continued). "Interestingly, APOB has been predicted as a causal gene in four related traits, coronary artery disease, LDL-C levels, triglyceride levels, and self-reported high cholesterol levels." (PMID 33499903, 2021). "In addition, the patients with GOF mutation of the PCSK9 gene showed higher risk of the coronary artery disease (CAD) in the FH patients compared to those with LDL-R mutation or apolipoprotein B (Apo B) mutation." (PMID 33123601, 2020). "In addition, we have demonstrated that high levels of IgM against methylglyoxal (MGO)-apoB-100 are associated with less severe and a lower risk of progression of coronary disease in subjects with type 2 diabetes." (PMID 25768285, 2015). "A link has been demonstrated between increased serum BCAA concentrations in humans and waist circumference, blood pressure, fasting blood glucose, TG, apolipoprotein B (apoB), apoB/apoAI ratio, apoCII and apoCI levels, which are important risk factors in coronary diseases." (PMID 25257998, 2014). "However, one investigation in Caucasian subjects reported lower concentrations of apolipoprotein B and reduced coronary artery disease risk in carriers of the T-allele compared with CC homozygotes." (PMID 23554669, 2011). "The early influence ofAPOB on apolipoprotein B levels is of particular interest from a cardiovascular disease prevention perspective, given that there is increasing evidence highlighting the crucial role it plays in coronary heart disease risk (Holmes & Ala-Korpela, 2019;Richardsonet al., 2020c)." (PMID 39301199, 2021). "Therefore, the ferulic acid intake could decrease the coronary heart disease risk associated with overweight and obesity via the reduction of the ApoB/ApoA1 ratio and LDL-C." (PMID 28661434, 2017). "For standard lipids, MVMR studies report an effect of apolipoprotein-B (ApoB) on coronary heart disease independently of LDL-C and TG." (PMID 40157129, 2025). "This study aims to evaluate the association between serum apoB levels and FRS, establishing its potential utility as a predictive biomarker for coronary artery disease (CAD) risk." (PMID 40852379, 2025). "A study from China involving 826 patients with coronary heart disease showed that ApoB/ApoA1 was still significantly correlated with the adjusted Gensini score." (PMID 40775270, 2025). "An MR study has indicated that ApoB is a keyfactor influencing the occurrence of coronary heart disease, distinct fromcholesterol and triglycerides." (PMID 40475729, 2025). "However, when testing for the presence of coronary atherosclerosis, the LDL/ApoB ratio was negatively associated with the disease (B = −0.593, p = 0.010, OR 0.553, 95% CI: 0.352–0.867, R2 = 0.096), suggesting that a lower ratio is linked to a greater likelihood of coronary disease." (PMID 41374382, 2025). "ApoB level was a stronger predictor of coronary artery disease (CAD) than LDL cholesterol, especially in insulin resistance and T2DM patients." (PMID 39355932, 2025). "We concentrated on 134 loci with nominal evidence (P < 0.05) of an association with apoB, as recent studies have highlighted the predominant role of apoB in coronary artery disease aetiology." (PMID 38448586, 2024). "According to a study conducted in the western region of Saudi Arabia, coronary artery disease patients with APOB-Xba I genotypes had significantly higher TC, LDL-C, and triglyceride values than controls." (PMID 39469407, 2024). "The genetically determined expression of HMGCR and the levels of LDC-C, APOB, and TC modified by HMGCR were associated with an increased risk of coronary artery disease." (PMID 38802400, 2024). "Variations in FN1 were related to coronary artery disease, myocardial infarction, circulating concentrations of cholesterol, apolipoprotein B, C-peptide, and waist-to-hip ratio with even “very strong” or “compelling” evidence of genetic support." (PMID 39143620, 2024).
coronary artery disease (continued). "In an early study by Bang and Dyerberg, Inuit living in West Greenland had lower serum levels of cholesterol, apolipoprotein B, and triglycerides and lower rates of coronary heart disease compared with Inuit living in Denmark but had prolonged bleeding times." (PMID 38288054, 2023). "IVW-MR association between LDL cholesterol mediated by gene HMGCR, PCSK9, NPC1L1 or APOB and coronary heart disease." (PMID 37528862, 2023). "We observed that testosterone increases the likelihood of high blood pressure only in females; and apolipoprotein B increases the likelihood of coronary atherosclerosis and major coronary heart disease events only in males." (PMID 36635277, 2023). "ACP-501 demonstrated good tolerability results in patients with stable coronary disease and is going through a phase II clinical trial designed to evaluate its impact on apoB metabolism in individuals with coronary heart disease (NCT03773172)." (PMID 36979690, 2023). "One study found that about half of the 231,986 people with coronary artery disease had low levels of apoB." (PMID 36439997, 2022). "Limonin has been found to significantly lower the level of apolipoprotein B(Apo-B), a potential marker for coronary artery disease, and this effect is greater than that of other citrus flavonoids." (PMID 36234762, 2022). "Although the crucial role of apoB in coronary heart disease is increasingly emerging, the comparative importance of apoB versus LDL cholesterol or triglycerides in other diseases remains less clear." (PMID 34729547, 2021). "Multivariable mendelian randomisation estimated that coronary heart disease and type 2 diabetes explained between 25% and 40% of the relationship between apoB and lifespan." (PMID 34729547, 2021). "Apolipoprotein B (apoB) is emerging as the crucial lipoprotein trait for the role of lipoprotein lipids in the aetiology of coronary heart disease." (PMID 34729547, 2021). "When comparing the accuracy of the prediction of coronary heart disease mortality based on apolipoprotein levels, they found that both apoB and the apoB/apoA1 ratio proved better than traditional cholesterol markers." (PMID 34677405, 2021). "High apoB/apoA-I ratio predicts multi-vessel (cut-off value of 0.82) coronary artery disease with complex lesion morphology." (PMID 32449038, 2020). "In particular, the significant decrease in mean fasting apolipoprotein B-48 levels in the 4-g group is encouraging, given that fasting serum apolipoprotein B-48 levels are significantly correlated (p < 0.0001) with the prevalence of coronary artery disease." (PMID 32200533, 2020). "Onat A, Ozhan H, Can G, Hergenç G, Karabulut A, Albayrak S. Serum apolipoprotein B is superior to LDL-cholesterol level in predicting incident coronary disease among Turks." (PMID 32049158, 2020). "It follows that apoB/apoA1 is positively correlated with the severity of coronary artery diseases and the prediction of long-term prognosis." (PMID 32539722, 2020). "APOB rs1042031(EcoRI) has been widely used to study coronary heart disease (CHD) and Steroid-Induced Osteonecrosis of the femoral head (SONFH)." (PMID 33005209, 2020). "The prognostic value of ApoB/A1 ratio was evaluated in the prospective cohort of 1639 coronary heart disease patients during a period of 5-year follow-up." (PMID 31744496, 2019). "Apolipoprotein B, which reflects the total mass of atherogenic particles like (VLDL, IDL, LDL) and its increase is associated with ischemic heart disease." (PMID 29805388, 2018).
coronary artery disease (continued). "Studies in humans and mice have identified clusterin in atherosclerotic plaques of the aorta, and clusterin levels were reported to correlate with serum paraoxonase and apolipoprotein B concentrations in Japanese men and women with coronary heart disease." (PMID 29534716, 2018). "This is supported by evidence that an increased plasma concentration of TG is associated with an elevated rate of coronary artery disease, increased low density lipoprotein (LDL) level, and increased cholesteryl ester transfer (HDL to apolipoprotein B)." (PMID 28644857, 2017). "Although CKD is associated with higher ratios of apoB/A-I, the association of CKD with coronary heart disease was similarly attenuated." (PMID 28957410, 2017). "Further work is required to investigate the impact of the APOB ins/del polymorphism on TRL metabolism, and coronary heart disease risk." (PMID 25793007, 2015). "Four gene variants related to lipid metabolism (including the rs562338 and rs503662 variants of the APOB gene, the rs7767084 variant of the LPA gene and the rs2246942 variant of the LIPA gene) have been shown to be associated with coronary heart disease (CHD)." (PMID 23653095, 2013). "A positive relationship between coronary heart disease and low density lipoprotein cholesterol with ApoB levels have been established." (PMID 19772655, 2009). "Notably, coronary artery disease (CAD) is positively associated with AD risk, potentially linked to elevated apolipoprotein B (APOB) levels." (PMID 40332115, 2025). "Furthermore, Mendelian randomization studies have revealed that apolipoprotein B is more dynamically representative of the association of TRLs and LDL-C and coronary heart disease (CHD)." (PMID 39752447, 2025). "In a recent analysis, which included over 3400 patients, apoB was strongly associated with coronary disease, and, along with other non-classical lipoprotein biomarkers, apoB added value to the standard lipid panel when it came to CV risk." (PMID 41374382, 2025). "Accordingly, aggregated ultra-rare variants in APOB were positively associated with both true and predicted MASLD/PDFF phenotypes, LiverRisk score, and cirrhosis, but negatively associated with serum apoB, cholesterol, and ischemic heart disease." (PMID 40065360, 2025). "After LASSO penalisation, 11 variables were retained: ECOG performance status, serum creatinine, apolipoprotein A, apolipoprotein B, coronary heart disease, prior VTE, central venous catheterisation, acute infection, G-CSF use, relapsed/refractory status, and red cell count." (PMID 41194009, 2025). "ApoB is present in LDL-C, whereas APOA1 is present in HDL-C; it has been suggested that an increase in Apo B concentrations and a decrease in Apo A1 concentrations are positively correlated with ischemic heart disease risk." (PMID 39683045, 2024). "An immunosensor for the detection of the coronary heart disease marker apolipoprotein B-100 (ApoB-100) was developed using a glass carbon electrode, functionalized with streptavidin, and 25 μL of biotinylated anti-ApoB-100 nanobody (BiNb4) at a concentration of 100 μg/mL." (PMID 37375810, 2023). "According to iCPAG, the highest enrichments were for beta blocking agent use (P = 1.36E-24), coronary artery disease (P = 2.70E-23), low-density cholesterol (P = 9.09E-21), myocardial infarction (P = 4.87E-20), apolipoprotein B (P = 1.24E-19) and parental longevity (P = 1.28E-19)." (PMID 35964012, 2022). "Genetic variations in the ApoB gene may lead to an increased the level of LDL particles and other lipid metabolic disorders, as well as an increased risk of coronary artery disease." (PMID 34156559, 2021).
coronary artery disease (continued). "The apoB/apoA1 ratio also showed improved accuracy over TC/HDL-C in predicting adverse cardiovascular events in a prospective study of patients with established coronary heart disease (CHD)." (PMID 34677405, 2021). "Likewise, the ability of apolipoprotein B (apoB)-depleted serum to accept cholesterol from macrophages was a predictor of mortality in patients with established coronary artery disease." (PMID 34441341, 2021). "Moreover, understanding the molecular mechanisms by which ApoB regulates angiogenesis will provide potential new therapeutic targets for the treatment of vascular pathologies ranging from cancer to ischemic heart disease." (PMID 34236046, 2021). "In fact, previous studies have demonstrated that apolipoprotein B, but not LDLc, was associated with the progression of carotid plaques or the future risk of coronary heart disease." (PMID 32660519, 2020). "The ApoB(apolipoprotein B) XbaI locus is not a risk factor when it comes to the development of coronary heart disease in the domestic and international populations included in this paper." (PMID 32493216, 2020). "Previously, increased ApoB level was found to be associated to larger plaque burden and larger presence of non-calcified plaques in patients with ischemic heart disease." (PMID 27004558, 2016). "C2ORF43 is functionally related to defective apolipoprotein b-100 and coronary heart disease." (PMID 26121138, 2015). "The present study aimed to assess the association between Apo A1 and ApoB and the severity of CAD and determine whether these parameters are better predictors of Ischemic Heart Disease (IHD)." (PMID 24757643, 2014). "Therefore, we believed the effects of lipids and lipoprotein on the normal weight and overweight groups were different, and apoB/apoA1 on the incidence of coronary heart disease among overweight subjects was a more meaningful prediction." (PMID 23554700, 2011). "Several large epidemiologic studies have found that apolipoproteins, especially apoB or the ratio of apoB to apoA-I, are superior to classic lipid profile constituents (i.e. total, HDL and/or LDL cholesterol) in predicting coronary heart disease risk/myocardial infarction in the general population." (PMID 19690648, 2007). "Apolipoprotein B (apoB), low-density lipoprotein cholesterol (LDL-C), and triglycerides (TG) are associated with coronary artery disease (CAD)." (PMID 38241044, 2024). "Do apolipoprotein B (apoB), low-density lipoprotein cholesterol (LDL-C), and triglycerides (TG) increase risk of coronary artery disease (CAD), all-cause mortality, or cause-specific mortality, and if so, what are the shapes of these associations?" (PMID 38241044, 2024). "Accumulating evidence indicated that apolipoprotein B (apoB) was the principal lipid determinant of coronary artery disease (CAD)." (PMID 37559117, 2023). "However, few studies have addressed the question of whether ApoB/A1 is related to the severity of coronary disease using a complex and systemic score, i.e., the Gensini score or SYNTAX score to predict the severity of coronary artery stenosis more accurately." (PMID 34961824, 2021). "Additionally, non-HDL considered a better risk marker for coronary heart disease exhibited a very strong correlation with ApoB and a strong correlation with oxidized LDL-c." (PMID 31409878, 2019). "Notably, mutations in the APOB gene may lead to elevated LDL levels and other lipid metabolic disorders as well as an increased risk of coronary heart disease owing to higher levels of serum APOB, even in the presence of normal levels of LDL." (PMID 28902930, 2017).
coronary artery disease (continued). "However, apolipoprotein A–I and apolipoprotein B may have an even stronger effect on coronary heart disease." (PMID 22629363, 2012). "In this study, we aimed to evaluate whether the apoB/apoA ratio can predict the presence and the severity of coronary artery disease (CAD) in a cohort from an Eastern European hospital, under moderate-intensity statin treatment." (PMID 41752696, 2026). "In terms of CMD, a noteworthy correlation was observed between the increase in the ApoB/ApoA1 ratio and various CMD, including ischemic heart disease, major adverse cardiovascular events, aortic aneurysm, cerebral ischemic disease and so on (all PFDR<0.05)." (PMID 38310324, 2024). "A recent study involving 17,532 American patients with coronary heart disease found that RLP-C correlated with myocardial infarction, coronary death, and stroke, even after controlling for LDL-C and apoB." (PMID 39720212, 2024). "For example, 11 significant genes contributing to heritability of ApoB are involved in pathways ranging from abnormal arterial stenosis to chylomicron, LDL and lipoprotein clearance, as well as hyperlipidemia and coronary artery diseases." (PMID 38336875, 2024). "ApoA1 was previously identified as a better predictor for ischemic heart disease and cardiovascular mortality than HDL, low-density lipoprotein, or apolipoprotein B." (PMID 36197585, 2023). "Apolipoprotein B (ApoB) and low-density lipoprotein cholesterol (LDL-C) were identified targets for blood lipid management among coronary artery disease (CAD) patients." (PMID 35146010, 2022). "This study was designed to determine the genetic polymorphism (rs676210) Pro2739leu G > A in the lipid metabolism-related gene (ApoB gene) and its pharmacogenetic role in the response to atorvastatin drug in a sample of Iraqi population with coronary artery disease (CAD)." (PMID 34156559, 2021). "In coronary artery disease, the higher the expression of miR-17 in patients, the higher the levels of TC, LDL-C, and ApoB in vivo." (PMID 34781979, 2021). "Our findings are in line with the findings of the Framingham Offspring Study, which identified apolipoprotein B and HDL cholesterol as major determinants of incident coronary heart disease." (PMID 22629363, 2012). "A recent MR study compared the effects of non-HDL-C (TC minus HDL-C) and ApoB on coronary artery disease and found that non-HDL-C captures the contribution of ApoB-containing particles to disease risk even better than the ApoB particle concentration." (PMID 40157129, 2025). "Multiple studies have shown that different lipid markers (such as LDL-C, HDL-C, ApoB, non-HDL-C, TG, etc.)are significantly associated with the GS, aiding in the risk assessment and prognostic management of coronary artery disease in ACS patients." (PMID 40775270, 2025). "The predictive value of apolipoprotein B (apo B) has been proven in the development of coronary artery disease (CAD) among normotensives only, but it has not been directly studied in hypertensive patients." (PMID 38169767, 2023). "In humans, apoB is important in preventing coronary heart disease and is a non-traditional lipid biomarker." (PMID 34305631, 2021). "Using antibodies recognizing oxidized phosphatidylcholine, including adducts with proteins that do not exhibit an apoB enhanced level of oxLDL, was reported in patients with coronary artery disease." (PMID 34110719, 2021). "Non-high-density lipoprotein cholesterol and apolipoprotein B in the prediction of coronary heart disease in men." (PMID 32049158, 2020). "In this population study, apoB/apoA‐I ratio was associated with risk of AVS incidence, especially in younger and female participants and those without concomitant coronary artery disease." (PMID 31407609, 2019).